ZMIZ2 (zinc finger MIZ-type containing 2)
Diseases named in the same sentence as ZMIZ2 in open-access papers:
ZMIZ2 is named in the same sentence as 23 diseases in open-access papers, as found by Europe PMC text mining. Sharing a sentence is not in itself a finding about the gene and the disease. The quoted sentences say what the papers report.
prostate carcinoma (5 papers, 2011 to 2026). A carcinoma that arises from epithelial cells of the prostate gland. "In the prostate cancer, ZMIZ2 interacts with β-catenin and improves β-catenin-mediated transcriptions." (PMID 38254216, 2024). "ZMIZ2, an androgen receptor (AR) transcriptional co-regulator, promotes prostate cancer (PCa) cell proliferation by interacting with AR to upregulate genes associated with cell proliferation; however, its specific cooperative mechanisms remain unclear." (PMID 41431399, 2026). "While aberrant ZMIZ2 expression has related to several cancer types, such as prostate cancer, breast cancer and colorectal cancer, its potential involvement in HCC remains unclear." (PMID 38254216, 2024). "ZMIZ2 is a PIAS-like protein, whose enhanced expression promotes tumor growth in multiple cancers, such as prostate cancer and CRC." (PMID 41502508, 2025). "Expression vectors for the human AR cDNA containing 9, 24, and 35 polyQ tracts and for AR cofactors, including ZMIZ1, ZMIZ2, and ARA70, were co-transfected with an androgen-induced luciferase reporter driven by a 7 Kb PSA promoter-enhancer fragment into prostate cancer cell line, DU145." (PMID 21949845, 2011). "Overall, this was first line of evidence that ZMIZ1, rather than ZMIZ2 or ARA70, enhances the ligand-induced transactivation of AR with shorter polyQ tract in prostate cancer cells." (PMID 21949845, 2011).
breast carcinoma (3 papers, 2022 to 2026). "Pan-cancer analysis revealed that the expression of ZMIZ2 was highly expressed in many types of cancers, such as bladder urothelial carcinoma, breast cancer, rectum adenocarcinoma, stomach adenocarcinoma, and head and neck tumor." (PMID 41431399, 2026). "Previous studies have shown that ZMIZ2 plays a role in the invasion and migration of breast cancer cells." (PMID 38254216, 2024). "The expression levels of ZMIZ2 were assessed in the three breast cancer cell lines and the breast epithelial cells." (PMID 35101047, 2022). "Moreover, based on the clinical samples, ZMIZ2 was confirmed to be upregulated in clinical breast cancer tissues and its high expression levels were correlated with a poor prognosis for TNBC patients." (PMID 35101047, 2022). "Moreover, ZMIZ2 was upregulated in clinical breast cancer tissues and its high expression was correlated with the poor prognosis of TNBC patients." (PMID 35101047, 2022). "Moreover, the correlation between ZMIZ2 and AR in different subtypes of breast cancers was calculated." (PMID 35101047, 2022). "To confirm our speculations, we downloaded RNA-seq data and clinical information for breast cancer from The Cancer Genome Atlas (TCGA) database and analyzed it for ZMIZ2 expression and the correlation between ZMIZ2 and AR." (PMID 35101047, 2022). "Furthermore, ZMIZ2 expression was increased in breast cancer cells, and a knockdown of ZMIZ2 inhibited MDA-MB-231 cell proliferation, migration, and invasion, induced cell cycle arrest in the G1 phase, and promoted cell apoptosis." (PMID 35101047, 2022). "The expression level of ZMIZ2 in the different breast cancer subtype tissue samples was quantified." (PMID 35101047, 2022). "Furthermore, in vitro experiments revealed that ZMIZ2 expression was increased in breast cancer cells, and the knockdown of ZMIZ2 inhibited MDA-MB-231 cell proliferation, migration, and invasion, induced cell cycle arrest in G1 phase, and promoted cell apoptosis." (PMID 35101047, 2022).
colorectal cancer (3 papers, 2020 to 2022). A primary or metastatic malignant neoplasm that affects the colon or rectum. "LINC00265 helps ZMIZ2 to stabilize β-catenin by acting as a sponge (and thereby inhibiting several miRNAs) in colorectal cancer, and it can be used to predict poor prognosis in acute myeloid leukemia patients." (PMID 32793593, 2020). "ZMIZ2 is a PIAS-like protein involved in prostate and colorectal cancer where it promotes tumor growth." (PMID 35051904, 2022).
triple-negative breast carcinoma (3 papers, 2022 to 2025). An invasive breast carcinoma which is negative for expression of estrogen receptor (ER), progesterone receptor (PR), and human epidermal growth factor receptor 2 (HER2). "Recent studies have revealed that ZMIZ2 is highly expressed in triple-negative breast cancer, and hepatocellular carcinoma and is associated with poor prognosis." (PMID 39266996, 2024).
hepatocellular carcinoma (2 papers, 2024). A malignant tumor that arises from hepatocytes. "Furthermore, the mRNA and protein expression of ZMIZ2 was highly increased in several hepatoma cell lines compared with immortalized LO2 human hepatocytes." (PMID 38254216, 2024).
lung carcinoma (2 papers, 2024 to 2025). "We explored the molecular mechanism by which ZMIZ2 promotes the malignant phenotype of lung cancer cells." (PMID 39266996, 2024). "Functional experiments revealed that ZMIZ2 promotes the proliferation, migration, and invasiveness of lung cancer cells—establishing its role as a promoter of oncogenes." (PMID 39266996, 2024). "These research findings not only elucidate the role of ZMIZ2 in promoting lung cancer progression through the Wnt and Hippo pathways but also suggest potential avenues for personalized treatments." (PMID 39266996, 2024). "ZMIZ2 promotes the malignant phenotype of lung cancer by regulating Wnt/Hippo pathways through SIRT1, providing an experimental basis for discovering novel biomarkers and developing tumor-targeted drugs." (PMID 39266996, 2024). "In our investigation of the molecular mechanism by which ZMIZ2 promotes the malignant phenotype of lung cancer cells, we found that ZMIZ2 significantly enhanced the expression of the key target genes associated with the Wnt pathway." (PMID 39266996, 2024). "Therefore, in this study, we investigated ZMIZ2 expression and its tumorigenic function in lung cancer." (PMID 39266996, 2024). "Functional assays conducted post-transfection with ZMIZ2 or ZMIZ2 sgRNA plasmids showed that ZMIZ2 might promote the proliferation and invasion capabilities of lung cancer cells." (PMID 39266996, 2024). "While our study substantiates the heightened ZMIZ2 expression in lung cancer tissues and cell lines compared with that of normal lung tissues, the specific mechanisms driving this upregulation remain unclear." (PMID 39266996, 2024). "Our study revealed elevated ZMIZ2 expression in various lung cancer cell lines and NSCLC cases." (PMID 39266996, 2024). "Moreover, colony formation and transwell assays clearly demonstrated that siRNA-SIRT1 transfection significantly abolished ZMIZ2-induced enhanced proliferative and invasive capabilities of lung cancer cells compared with individual transfection." (PMID 39266996, 2024). "Additionally, western blotting analysis was performed on 32 pairs of fresh lung cancer tissues and their adjacent tissues, revealing that protein expression of ZMIZ2 in cancer tissues was significantly higher than that in the adjacent tissues (24/32) (P < 0.0001)." (PMID 39266996, 2024). "To explore the expression and biological role of ZMIZ2 in NSCLC, we performed immunofluorescence, IHC, and western blotting analyses using established lung cancer cell lines and clinical samples." (PMID 39266996, 2024). "To further explore the impact of ZMIZ2 on malignant phenotypes, such as invasion and proliferation in lung cancer, we manipulated ZMIZ2 expression in NCI-H1299 (relatively low ZMIZ2 expression) and Calu-1 (high ZMIZ2 expression) cell lines." (PMID 39266996, 2024). "The interaction between ZMIZ2 and SIRT1 results in the activation of the Wnt pathway and inhibition of the Hippo pathway, thereby promoting the biological phenotypes of lung cancer, including cell proliferation, invasion, and metastasis." (PMID 39266996, 2024). "In addition, laser confocal microscopy experiments showed that ZMIZ2 and SIRT1 colocalized within the tumor nucleus across various lung cancer cell lines." (PMID 39266996, 2024).
lymph node metastasis (2 papers, 2024 to 2025). "ZMIZ2 was highly expressed in NSCLC and positively associated with advanced pTNM staging, lymph node metastasis, and poor overall survival." (PMID 39266996, 2024).
colon cancer (1 paper, 2023). "For example, ZMIZ2 promoted tumour proliferation of colon cancer by recruiting USP7, deubiquitinating β‐catenin, and thereby activating WNT signalling pathway." (PMID 38073586, 2023).
prostate tumors (1 paper, 2026). "Subcutaneous xenograft tumor assays using LNCaP cells in nude mice further validated that ZMIZ2 drives prostate tumor proliferation through AR signaling." (PMID 41431399, 2026).
prostatic hyperplasia (1 paper, 2026). "The expression levels of ZMIZ2 in benign prostatic hyperplasia cells (BPH1) and PCa cells (LNCaP) were detected." (PMID 41431399, 2026).
renal carcinoma (1 paper, 2024). A carcinoma arising from the epithelium of the renal parenchyma or the renal pelvis. "Besides, ZMIZ2 was screened to be the target gene regulated by the IGF2BP3/circRARS complex in an m6A-dependent manner in renal carcinoma." (PMID 39266996, 2024).
tumor (10 papers, 2013 to 2026). "The tumor size and weight were significantly reduced after ZMIZ2-knockdown, indicating that ZMIZ2 deficiency inhibited HCC tumor development in vivo." (PMID 38254216, 2024). "In addition, HE staining showed that ZMIZ2 overexpression increased nuclear division and relieved inflammatory cell infiltration in tumor tissues, whereas MCM3 knockdown caused evident interstitial fibrosis." (PMID 41502508, 2025). "The absence of AR expression remarkably attenuates the effect of ZMIZ2 in promoting tumor cell proliferation." (PMID 41431399, 2026). "At present, more and more research results show that ZMIZ2 is highly expressed in a variety of tumor tissues." (PMID 41431399, 2026). "It is also upregulated in various cancer types, and studies have shown that the high ZMIZ2 expression is positively correlated with tumor cell proliferation." (PMID 41431399, 2026). "ZMIZ2, a downstream target of SGK3, stabilizes β-catenin and promotes tumor progression, which has been linked to poor prognosis in estrogen receptor-positive breast cancer." (PMID 41502508, 2025). "Overall, these data implied that ZMIZ2 contributed to TNBC tumor growth in vivo by regulating MCM3 expression." (PMID 41502508, 2025). "The expression levels of MCM3, BCL2, and N-cadherin increased, whereas those of cyclin A, BAX, and E-cadherin decreased in ZMIZ2-overexpressing tumor tissues." (PMID 41502508, 2025). "MCM3 knockdown reversed the effect of ZMIZ2 overexpression on TNBC tumor growth both in vitro and in vivo." (PMID 41502508, 2025). "Simultaneously, tumor growth in the ZMIZ2-OE+ CM3-sh group was significantly inhibited compared to that in the ZMIZ2-OE group." (PMID 41502508, 2025). "The growth curve of xenografted TNBC tumors in mice showed that with an increase in the number of days, the tumor volume increased after ZMIZ2 overexpression but remarkably decreased after MCM3 knockdown." (PMID 41502508, 2025). "Patients with tumor diameter <2.0 cm exhibited a significantly lower ZMIZ2 expression level than those with tumor diameter >2.0 cm (p < 0.001)." (PMID 41502508, 2025). "ZMIZ2 enhances the transcriptional activity of androgen receptor(AR), which is highly expressed in HCC and is associated with increased tumor recurrence and decreased overall survival." (PMID 38254216, 2024). "Consistently, the infiltration levels of those anti-tumor immune cells were significantly decreased in the ZMIZ2 high expression groups, while the infiltration scores of CD4 T cells and DCs were higher." (PMID 38254216, 2024). "In contrast, ZMIZ2 expression was significantly negatively correlated with the infiltration of multiple anti-tumor immune cells, such as NK cells, CD8 T cells, and Th1 cells." (PMID 38254216, 2024). "The results revealed that, in addition to the previously reported interaction with β-catenin, ZMIZ2 also binds to the deacetylase SIRT1, which is closely associated with tumor progression." (PMID 39266996, 2024). "As one of PIAS-like proteins, ZMIZ2 has been revealed to interact with β-catenin physically, augmenting β-catenin-mediated transcription and tumor cell growth." (PMID 35860547, 2022). "Though no common somatic variants were found between primary tumors of SBL and HB, in-frame deletion of PAN3 and ZMIZ2 were identified in both tumor samples after treatment." (PMID 35860547, 2022). "In addition, tumor weight showed similar changes; the tumor weight increased after ZMIZ2 overexpression, but remarkably decreased after MCM3 knockdown." (PMID 41502508, 2025). "We next investigated the tumor somatic alterations between high and low ZMIZ2 expression groups." (PMID 38254216, 2024). "The disruption of ZMIZ2 in tumor tissues of both SBL and HB may lead to down-regulation of β-catenin downstream targets and inhibition of the Wnt signaling pathway after treatment." (PMID 35860547, 2022).
tumor (continued). "However, studies on the function of ZMIZ2 remain limited; its expression pattern, clinical significance and regulatory role in tumor-associated signaling pathways have not been fully elucidated." (PMID 41431399, 2026). "Moreover, ZMIZ2 expression increased with increasing tumor–node–metastasis (TNM) stage (p = 0.002)." (PMID 41502508, 2025). "However, the role of ZMIZ2 in HCC tumor immunity deserves further exploration." (PMID 38254216, 2024). "To further verify the relationship between ZMIZ2 and MCM3 in vivo, we established a mouse xenograft model and monitored tumor growth." (PMID 41502508, 2025). "To further elucidate the regulatory mechanism of the ZMIZ2/MCM3 axis in promoting TNBC, we performed RNA sequencing of tumor tissues from a xenograft mouse model in the control, MCM3-sh, and ZMIZ2-OE groups." (PMID 41502508, 2025). "To further explore the potential mechanism of the ZMIZ2/MCM3 axis in promoting TNBC, we performed RNA sequencing of tumor tissues from a xenograft mouse model in the control, MCM3-sh, and ZMIZ2-OE groups." (PMID 41502508, 2025). "Overall, the evidence from in vitro and in vivo experiments demonstrates that ZMIZ2 functions as an oncogene in NSCLC, enhancing its biological role and promoting malignant phenotype of tumor cells." (PMID 39266996, 2024). "Although the role of ZMIZ2 in TNBC is yet to be fully explored, its involvement in key signaling pathways suggests that inhibiting its function could interfere with tumor growth and metastasis, offering a potential therapeutic strategy." (PMID 41502508, 2025). "Additionally, GSVA analysis revealed an activation of tumor progression-related pathways, including DNA repair, PI3K/AKT/MTOR signaling, and Wnt/β-catenin signaling, in the high-ZMIZ2 group." (PMID 38254216, 2024). "We hypothesized that tumors without activating oncogenic insertions in the Zmiz1 or Zmiz2 genes would have higher frequencies of inactivation of the tumor suppressor genes found in the Onc2.3 system." (PMID 33435458, 2021).
cancer (6 papers, 2021 to 2026). A tumor composed of atypical neoplastic, often pleomorphic cells that invade other tissues. "To validate this finding, we performed western blotting to detect the expression of key proteins associated with these pathways in cancer cells upon alteration of ZMIZ2 expression." (PMID 39266996, 2024). "The results demonstrated that the expression level of ZMIZ2 in PCa tissue was significantly increased, and the positive staining area essentially coincided with the accumulation area of cancer cells." (PMID 41431399, 2026). "Given the important role of ZMIZ2 in cancer biology, our findings offer novel perspectives on the molecular mechanisms underlying TNBC and pave the way for the development of innovative therapeutic approaches." (PMID 41502508, 2025). "A pan-cancer analysis of ZMIZ2 mRNA expression levels in 26 common human cancers showed that ZMIZ2 was overexpressed in various tumors compared with adjacent normal tissue (logFC > 0)." (PMID 38254216, 2024). "qRT-PCR revealed that ZMIZ2 mRNA was significantly upregulated in cancer tissues in comparison with the controls (P < 0.05)." (PMID 35101047, 2022). "Based on data from The Cancer Genome Atlas (TCGA), the expression of ZMIZ2 in different subtypes and its correlation with androgen receptor (AR) were analyzed, and a regulatory mechanism network was constructed." (PMID 35101047, 2022). "Zinc finger MIZ-type containing 2 (ZMIZ2) can function as a coactivator and participate in the progression of certain malignant tumors; however, its expression and underlying molecular mechanism in non-small-cell lung cancer (NSCLC) remains unknown." (PMID 39266996, 2024). "Moreover, consistent results were obtained from western blot and immunohistochemistry: protein expression levels of ZMIZ2 were significantly increased in cancer tissues, especially the TNBC tissues, when compared with the control (P < 0.05)." (PMID 35101047, 2022). "The results indicated that ZMIZ2 was highly expressed in cancer tissues but relatively low in adjacent noncancer tissues." (PMID 41431399, 2026). "We found negative correlations between ZMIZ2 and AR in the cancer tissue samples (r < 0), while the correlation was positive in the normal tissue samples (r > 0)." (PMID 35101047, 2022). "Moreover, the data from 52 paired samples indicated that the mRNA expression level of ZMIZ2 in cancer tissues was remarkably higher than that in adjacent noncancerous tissues (p < 0.001)." (PMID 41431399, 2026).
ZMIZ2 also shares sentences with these, for which no sentence is quoted: acute myeloid leukemia (1 paper); adenocarcinoma (1); Alzheimer disease (1); bladder urothelial carcinoma (1); head and neck tumor (1); immune disease (1); lung adenocarcinoma (1); non-small cell lung carcinoma (1); rectum adenocarcinoma (1); stomach adenocarcinoma (1).